NENF (neudesin neurotrophic factor)
Description:
Acts as a neurotrophic factor in postnatal mature neurons enhancing neuronal survival. Promotes cell proliferation and neurogenesis in undifferentiated neural progenitor cells at the embryonic stage and inhibits differentiation of astrocytes (By similarity). Its neurotrophic activity is exerted via MAPK1/ERK2, MAPK3/ERK1 and AKT1/AKT pathways (By similarity). Neurotrophic activity is enhanced by binding to heme (By similarity). Also acts as an anorexigenic neurotrophic factor that contributes to energy balance (By similarity).
Synonyms: CIR2; SPUF; SCIRP10
Tractability: Antibody: UniProt places it where antibodies can reach, with high confidence; UniProt predicts a signal peptide or a membrane-spanning region; its Gene Ontology location is reachable by antibodies, with medium confidence. PROTAC: ubiquitination databases record sites on it; its protein half-life has been measured.
Gene: Protein-coding gene on chromosome 1 (212,432,853 to 212,446,379, forward strand). Ensembl gene ENSG00000117691.
Subcellular location: Secreted, extracellular space; Mitochondrion; Endoplasmic reticulum
Gene Ontology:
Molecular function: protein binding; growth factor activity
Biological process: negative regulation of appetite; signal transduction
Cellular component: endoplasmic reticulum; extracellular region; mitochondrion
Genetic constraint (gnomAD): Loss-of-function variants: 5 observed, 8.44 expected, observed/expected ratio (o/e) 0.59, 90% interval 0.31 to 1.24. That is too few expected variants to judge how well the gene tolerates losing a copy. Missense variants: 153 observed, 169.41 expected, observed/expected ratio (o/e) 0.9, 90% interval 0.79 to 1.03. Synonymous variants: 62 observed, 66.71 expected, observed/expected ratio (o/e) 0.93, 90% interval 0.76 to 1.15.
Homologues: Orthologues: chimpanzee NENF (100% identical), macaque NENF (99% identical), mouse Nenf (91% identical), pig NENF (90% identical), dog NENF (90% identical), rabbit NENF (88% identical), tropical clawed frog nenf (62% identical), zebrafish nenf (59% identical).
Diseases named in the same sentence as NENF in open-access papers:
NENF is named in the same sentence as 15 diseases in open-access papers, as found by Europe PMC text mining. Sharing a sentence is not in itself a finding about the gene and the disease. The quoted sentences say what the papers report.
breast carcinoma (6 papers, 2008 to 2025). "E2 treatment affects the expression of NENF mRNA differently; in rat hepatic cells it is decreased, but in breast cancer cell lines it is elevated." (PMID 39598420, 2024). "NENF also increases the tumorigenicity and invasiveness of MCF-7 breast cancer cells." (PMID 37894441, 2023). "In addition, ectopic expression of NENF in MCF7 cells promotes invasiveness and tumorigenesis of breast cancer cells." (PMID 31835509, 2019). "The role of NENF in cancer biology, progression, or metastasis has not been extensively investigated, but it has been proposed that it may play a significant role in the development of liver, bladder, and breast cancers." (PMID 37894441, 2023).
liver cancer (2 papers, 2022 to 2023). An epithelial or non-epithelial malignant neoplasm that arises from the liver. "The depletion of NENF has been shown to reduce cancer cell growth and invasiveness and impair the ability of liver cancer cells to form tumors in mice." (PMID 37894441, 2023). "In Europeans, C10orf143 had a lower proportion of Neanderthal introgression among liver cancer patients compared to the general population and in East Asians, NENF and TEDC1 showed a similar pattern." (PMID 36503519, 2022). "In East Asians, there were two genes with a significant depletion of Neanderthal introgression in liver cancer patients compared to non-affected individuals—NENF (p-value = 3.32 × 10–8, adjusted p-value = 0.0001) and TEDC1 (p-value = 1.11 × 10–5, adjusted p-value = 0.038)." (PMID 36503519, 2022).
Achalasia (1 paper, 2023). A disorder of esophageal motility characterized by the inability of the lower esophageal sphincter to relax during swallowing and by inadequate or lacking peristalsis in the lower half of the body of the esophagus. "Analysis of DEGs showed the upregulations of PPDPF, NENF, and CYBA and downregulations of FOS, DUSP1, and GPX1 in peripheral blood myeloid cells of achalasia." (PMID 37542039, 2023).
Anxiety (1 paper, 2024). Intense feelings of nervousness, tension, or panic often arise in response to interpersonal stresses. "Studies relating to NENF are primarily relegated to its function in the brain, such as regulating anxiety and food intake." (PMID 39598420, 2024).
brain tumors (1 paper, 2023). "Our previous study showed elevated concentrations of NENF in the cerebrospinal fluid of patients with astrocytic brain tumors compared to non-tumoral controls, suggesting NENF as a circulating biomarker for brain tumors." (PMID 37894441, 2023).
colorectal cancer (1 paper, 2023). A primary or metastatic malignant neoplasm that affects the colon or rectum. "A receiver operator characteristic (ROC) curve analysis showed that the serum NENF score significantly differentiated the colorectal cancer patients from the healthy controls with a diagnostic sensitivity and positive predictive value of 83% and 81%, respectively." (PMID 37894441, 2023). "We assessed the NENF expression in colorectal cancer and its release in CRC tissues and DLD-1 and HT-29 cell lines." (PMID 37894441, 2023). "Targeting the PGRMC1/NENF complex may open-up new therapeutic possibilities for patients with advanced colorectal cancer." (PMID 37894441, 2023). "Progesterone (P4) via PGRMC1/NENF may stimulate the proliferation and invasion of colorectal cancer DLD-1 and HT-29 cells." (PMID 37894441, 2023). "Targeting the PGRMC1/NENF complex may open-up new therapeutic possibilities for patients with colorectal cancer." (PMID 37894441, 2023). "Our data may provide the novel insights into the action of P4, PGRMC1, and NENF in colorectal cancer." (PMID 37894441, 2023). "Taken together, our data provided novel insights into the actions of P4, PGRMC1, and NENF in colorectal cancer, emphasizing new potential actions that may regulate CRC biology." (PMID 37894441, 2023). "Moreover, NENF, as a secreted protein, could become a promising circulating biomarker candidate to distinguish between colorectal cancer patients and healthy individuals." (PMID 37894441, 2023). "Furthermore, NENF, as a secreted protein, potentially could serve as a promising circulating biomarker candidate for distinguishing between colorectal cancer patients and healthy individuals, although large-scale extensive studies are needed to establish this." (PMID 37894441, 2023). "Therefore, future studies aimed at developing treatment strategies for colorectal cancer could consider simultaneous PGRMC1 inhibition along with a blockage of NENF production and secretion." (PMID 37894441, 2023). "We examined the effects of P4 and NENF on the cell proliferation and invasion of DLD-1 and HT-29 colorectal cancer." (PMID 37894441, 2023). "Additionally, we showed that P4 increased the NENF secretion in the CRC cells, which suggests a direct effect of P4 on NENF production in colorectal cancer." (PMID 37894441, 2023). "A diagnostic analysis revealed the usefulness of serum NENF levels in identifying CRC patients from those without cancer, suggesting its potential role as a circulating biomarker for colorectal cancer." (PMID 37894441, 2023). "Additionally, we analyzed the P4 and NENF treatment effects on the cell proliferation and invasion of DLD-1 and HT-29 colorectal cancer cells." (PMID 37894441, 2023).
diabetes (1 paper, 2023). "For instance, TXNDC5’s interactions with NENF, PPP1R2, ALDOC, LDH, or PGD may help explain its relevance in diabetes." (PMID 38138960, 2023).
neuroblastoma (1 paper, 2019). Neuroblastoma (NB) is the most common solid, extracranial childhood tumor. "To investigate this, we attempted to detect endogenous NENF secretion in ECSCs and DNLCs and found that NENF was discernible in conditioned culture medium and cell lysates, as previously reported in mouse neuroblastoma cells." (PMID 31536960, 2019).
Parkinson disease (1 paper, 2019). A progressive degenerative disorder of the central nervous system characterized by loss of dopamine producing neurons in the substantia nigra and the presence of Lewy bodies in the substantia nigra and locus coeruleus. "We also find that a heme-containing neurotrophic factor, neuron-derived neurotrophic factor [NENF], couples with Parkinson disease-related proteins to promote neurotrophic activity." (PMID 31536960, 2019).
cancer (6 papers, 2006 to 2025). A tumor composed of atypical neoplastic, often pleomorphic cells that invade other tissues. "However, another gene NENF, previously being reported as promoting cancer development, was downregulated, suggesting the complexity of tumor immune microenvironment in a high prognostic risk scenario." (PMID 32950055, 2020). "Three corresponded to genetic determinants of genetic syndromes (MTMR, DISC1, MTX1) and the three others bore functions with no obvious link to cancer (NENF, ENSA, TARBP1)." (PMID 17060936, 2006).
tumor (3 papers, 2020 to 2025). "For instance, NENF is involved in protease-mediated neural differentiation in neural precursor cells, and its ectopic expression in macrophages cytolytic factor cells promotes tumor incidence." (PMID 38739480, 2024).
NENF also shares sentences with these, for which no sentence is quoted: breast tumors (1 paper); Cognitive impairment (1); Obesity (1); triple-negative breast carcinoma (1).